SNORD83B (small nucleolar RNA, C/D box 83B)
Synonyms: U83B; RNU83B
Gene: Small nucleolar RNA gene on chromosome 22 (39,313,819 to 39,313,911, reverse strand). Ensembl gene ENSG00000209480.
Gene Ontology:
Biological process: RNA processing
Cellular component: nucleolus
Homologues: Orthologues: chimpanzee SNORD83B (100% identical), macaque SNORD83B (99% identical), guinea pig SNORD83B (94% identical), mouse Snord83b (91% identical), rat Snord83b (91% identical), rabbit SNORD83B (75% identical), pig SNORD83B (70% identical). Paralogues in human: SNORD83A (81% identical).